ALB (albumin)
Diseases named in the same sentence as ALB in open-access papers (continued):
Sharing a sentence is not in itself a finding about the gene and the disease.
injury (continued). "Finally, furosemide is highly bound to plasma protein, and the addition of albumin to furosemide therapy in hypoproteinemic patients with acute lung injury avoids worsening of FO with better maintenance of hemodynamic stability, as compared with furosemide therapy alone." (PMID 33585362, 2020). "HO-1, an inducible isozyme, is activated by heme, oxidants, cytokines, glycated albumin, and other stressors, and may be part of the protective response in many diseases, including acute lung injury, lipopolysaccharide-induced acute liver failure, neurodegenerative disorders, and AKI." (PMID 26866373, 2016). "For instance, in a canine CCl4-induced acute liver injury model, canine ADSCs similarly significantly reduced serum AST and ALT levels; in sodium diclofenac-induced rat liver injury, rat ADSCs also effectively improved ALT, AST, and ALB indicators." (PMID 41465230, 2025). "This study aimed to evaluate the prognostic value of key inflammatory and metabolic biomarkers: platelet-to-lymphocyte ratio (PLR), C-reactive protein-to-albumin ratio (CAR), serum lactate, base deficit, and neutrophil-to-lymphocyte ratio (NLR) in relation to ICU mortality in trauma patients." (PMID 41010921, 2025). "While albumin products have been used experimentally for the treatment of hemorrhagic shock use of hypo-oncotic, 4% albumin solution was not advantageous in treating people with traumatic brain injury." (PMID 34026881, 2021). "The serum AST, ALT, total protein, albumin levels, and A/G ratio, which are the indices of liver injury did not change when the rats were fed with 5% ethanol for 5 weeks, demonstrating that there was no ethanol-induced liver injury." (PMID 31211011, 2019). "In addition, there is a negative relationship between albumin levels and levels of neutrophil gelatinase‐associated lipocalin (NGAL), which is commonly associated with inflammation and kidney injury and is recognized as a biomarker for renal function and damage." (PMID 38402549, 2024).
lymphoma (43 papers, 2010 to 2025). A malignant (clonal) proliferation of B- lymphocytes or T- lymphocytes which involves the lymph nodes, bone marrow and/or extranodal sites. "Many studies have demonstrated that albumin is a risk parameter for the prognosis of some diseases, such as gastrointestinal stromal tumors, human immunodeficiency virus, lymphoma, and cutaneous malignant melanoma." (PMID 36874101, 2023). "Old age (≥80 years), poor performance status, low serum albumin level, and comorbidities were the major factors associated with less intensive anti-lymphoma treatment." (PMID 34579119, 2021). "Serum ALB <35 g/L was also reported as a risk factor in the risk model for CNS relapse of high-grade lymphoma." (PMID 27624700, 2016). "We speculate that slight decrease of serum albumin level may be caused by increase of inflammatory cytokines secretion and vascular permeability which is induced by systemic inflammatory states in lymphoma patients." (PMID 29291712, 2018). "A previous study demonstrated improvements in serum albumin levels and Mini Nutritional Assessment scores in patients with malignant lymphoma after chemotherapy." (PMID 38400912, 2024). "Imaging of the tumor burden has been explored in lymphoma xenograft models by labeling albumin-based NPs coated with rituximab and the Alexa Fluor 750 fluorochrome." (PMID 39273202, 2024). "The lymphoma subtype, platelets, albumin, LDH, and creatinine were also independent prognostic factors for the 60‐day survival." (PMID 39219182, 2024). "This study also found that post-treatment serum albumin at 4 weeks strongly affected overall survival in dogs with multicentric lymphoma treated with the L-COP protocol." (PMID 38595652, 2024). "Other factors such as having leukemia, lymphoma, a reduced albumin, a reduced AMC, and an elevated AST were also independently associated with COVID‐19–related hospitalization." (PMID 38063366, 2023). "In this study, the use of serum CRP was compared with pre-treatment albumin and circulating inflammatory markers in lymphoma dogs at various stages." (PMID 36718344, 2022). "The prognostic value of serum albumin in acquired immunodeficiency syndrome (AIDS)-related lymphoma (ARL) remains covered." (PMID 35717275, 2022). "Elevated serum Hp concentrations and low concentrations of serum albumin was observed in our study, similar to the previous reports of canine high-grade multicentric lymphomas." (PMID 35765478, 2022). "Studies on HIV-negative lymphoma have found that nutritional status indicators, such as body mass index (BMI), serum albumin (ALB), serum prealbumin (PA), and hemoglobin (Hb), can be used as prognostic risk factors for lymphoma." (PMID 36438738, 2022). "This study aimed to examine pre-treatment serum CRP levels in relation to serum albumin and other circulating inflammatory parameters in dogs with advanced-stage lymphoma." (PMID 36718344, 2022). "A key question is, if low serum albumin levels in these patients are a consequence or one of the reasons for the more aggressive course of the lymphoma with impaired outcome." (PMID 35847697, 2020). "The literature is controversial about reduced albumin synthesis or degradation in cancer and lymphoma patients." (PMID 35847697, 2020). "For SMZL patients, we computed the specific prognostic score SMZL IIL (Italian Lymphoma Group) using hemoglobin, albumin, and lactate dehydrogenase (LDH)." (PMID 31892196, 2019). "The median albumin concentration in the CSF of patients with lymphoma was 243 mg/l (52.5–9727), and it was 193 mg/l (105.5–1099) in the non-lymphoma group." (PMID 25697593, 2015). "The most specific test to separate groups with lymphoma CNS involvement from other patient groups was the CSF AT III/ albumin ratio." (PMID 25697593, 2015). "Antitumor activity was only observed in the albumin fraction, which inhibited the growth of cells in murine lymphoma L5178Y." (PMID 20961452, 2010).
lymphoma (continued). "In our patient, mild changes were noted in liver enzymes (ALT), total proteins, and albumin levels, consistent with findings in other lymphoma cases, which often show hypoproteinemia due to reduced albumin and globulin, as well as altered serum calcium, urea, and creatinine." (PMID 40005863, 2025). "The prognostic significance of low serum albumin has been reported in patients with various lymphoma subtypes, including high-grade lymphoma, follicular lymphoma, intestinal lymphomas, adult T-cell leukemia/lymphoma, peripheral T-cell lymphoma, and Hodgkin lymphoma." (PMID 40740777, 2025). "Age, sex, ECOG score, Lugano stage, B symptoms, pathological subtypes, IPI score, leukocyte, serum LDH, albumin, β2 microglobulin, Ki-67, lymphoma site, first-line treatment and other indicators of 88 PI-DLBCL patients were included in the COX regression model for PFS univariate analysis." (PMID 39211552, 2024). "Age, sex, ECOG score, Lugano stage, B symptoms, pathological subtypes, IPI score, leukocyte, serum LDH, albumin, β2 microglobulin, Ki-67, lymphoma site, first-line treatment and other indicators of 88 PI-DLBCL patients were included in the COX regression model for OS univariate analysis." (PMID 39211552, 2024). "Furthermore, lymphoma and leukemia cell lines package albumin into small and lipid-like entities that are likely EVs, which inhibit T-cell activation, proliferation, and function." (PMID 36470535, 2023). "The erythrocyte sedimentation rate (ESR), C-reactive protein (CRP), neutrophil-to-lymphocyte ratio (NLR), platelet-to-lymphocyte ratio (PLR), lactate dehydrogenase (LDH), total protein (TP), and albumin were assessed in 706 patients with newly diagnosed or relapsed lymphoma." (PMID 35439998, 2022). "Serum albumin was significantly lower in lymphoma than in control dogs (p=0.0002)." (PMID 35765478, 2022). "As such, the serum levels of Hp and albumin are useful for the prognosis in dogs with lymphoma." (PMID 35765478, 2022). "The median albumin concentration in lymphoma dogs in this study was 2.6 g/dL (Table-3)." (PMID 36718344, 2022). "The degree of a perturbed albumin turnover in cancer or lymphoma patients is controversial." (PMID 35847697, 2020). "Since CXCR4 plays a central role in B‐cell homing and cancer cell migration, it is intriguing to speculate that normal albumin levels might be necessary to generate sufficient EPI‐X4 levels to impair lymphoma migration." (PMID 35847697, 2020). "This correlation between serum albumin and gastric complications may indicate that the serum albumin level is a surrogate marker for severity of lymphoma in the stomach." (PMID 30730104, 2019). "Similarly, antitumor activity was also observed in the albumin fraction, which inhibits the growth of cells in murine lymphoma, documenting one of the earliest reports on biological activity of semifermented-dry cocoa protein fractions." (PMID 30791360, 2019). "We want to emphasize that nonspecific clinical findings as fever and progressive deteriorated general conditions in combination with elevated LDH and low albumin levels should should raise the suspicion for lymphoma in general and after exclusion of these even for rare lymphoma like IVLBCL." (PMID 26670158, 2015). "Both CSF AT III and albumin levels were higher in lymphoma patients with CNS involvement." (PMID 25697593, 2015). "Low albumin levels are associated with poor general health, inflammation, and low body mass index (BMI) and are generally related to poor survival in patients independent of lymphoma." (PMID 37833260, 2023). "Finally, the albumin fraction also shows antitumor activity in a mouse murine model of lymphoma L5178Y, indicating that it could be considered as a source of potential antitumor peptides." (PMID 30791360, 2019).
lymphoma (continued). "A retrospective study of 807 patients with acute or lymphoma ATL diagnosed between 2000 and 2009 at 81 institutions across Japan identified clinical stage, performance status, age, albumin, and soluble interleukin 2 receptor (sIL-2R) as prognostic factors." (PMID 40465105, 2025). "Among ATL subtypes, acute, lymphoma and chronic ATL with unfavorable prognostic factors (among high LDH, low albumin, and high BUN) are referred to as aggressive ATL, and should be treated with combination chemotherapy (CQ1, 2)." (PMID 40465105, 2025). "The NLR, PLR, ESR, CRP, and LDH were significantly higher in the patients with lymphoma with VTE, whereas the TP and albumin were significantly lower in those patients." (PMID 35439998, 2022). "In particular, the univariate regression analysis indicated that the NLR, PLR, TP, albumin, LDH, and CRP were prognostic factors for VTE development in the patients with lymphoma." (PMID 35439998, 2022). "In the univariate regression analysis, the NLR, PLR, TP, albumin, LDH, and CRP were found to be prognostic factors for VTE development in the patients with lymphoma." (PMID 35439998, 2022). "CSF AT III levels were shown to be higher in lymphoma patients with CNS involvement, when AT III/albumin ratios were lower." (PMID 25697593, 2015). "In this model, the presence of low albumin levels, high LDH and bone marrow involvement by the lymphoma predicted a 72% rate of febrile neutropenia with full dose of CHOP as the therapeutic regimen." (PMID 25909361, 2015). "Serum albumin level can serve as a simple negative prognostic indicator of survival outcomes in dogs with high-grade multicentric lymphoma treated with the L-COP protocol." (PMID 38595652, 2024). "In addition to lymphoma subtypes, we also analyzed the prognostic roles of age, hemoglobin, neutrophil counts, platelets, fibrinogen, LDH, ferritin, albumin, and creatinine." (PMID 39219182, 2024). "Compared with patients without VTE, the NLR, PLR, ESR, CRP, and LDH were significantly higher in the patients with lymphoma with VTE (p = 0.001, p = 0.001, p = 0.023, p < 0.001, and p = 0.035, respectively), whereas the TP and albumin were significantly lower (p = 0.024 and p = 0.032, respectively)." (PMID 35439998, 2022). "We measured with ELISA CSF and serum AT III and albumin levels in 12 lymphoma patients with CNS involvement, 30 lymphoma patients without CNS involvement, and 41 patients with non-neoplastic neurological diseases." (PMID 25697593, 2015). "We found low serum AT III levels in lymphoma patients, which might explain the low CSF AT III/ albumin ratio in these patients." (PMID 25697593, 2015). "The univariate analysis identified that the lymphoma and HIV-related parameters, including LDH, ECOG PS, Ann Arbor stage, bulky mass, B symptoms, IPI, aaIPI, NCCN-IPI, CD4 T-cell count, erythrocyte sedimentation rate (ESR), and albumin (ALB), had a significant impact on OS (all P < 0.05)." (PMID 35873145, 2022). "In our study, the NLR, PLR, ESR, CRP, and LDH were significantly higher in the patients with lymphoma with VTE than in those without VTE, whereas the TP and albumin were significantly lower in the patients with lymphoma with VTE than in those without VTE." (PMID 35439998, 2022). "OCI patients had lower levels of total protein and serum albumin and higher ALT and AST compared with lymphoma patients without OCI." (PMID 35454063, 2022). "When comparing this ratio in the different groups of patients with PCNSL, secondary CNS lymphoma, systematic lymphoma without CNS involvement, and non-lymphoma patients, patients with systemic lymphoma without CNS lesion had the highest AT III/albumin ratio (p < 0.001)." (PMID 25697593, 2015). "The difference between AT III (AUC = 0.791, p = 0.002) and albumin (AUC = 0.839, p < 0.001) was not clear, indicating that AT III is not a novel biomarker that could be used to select patients with lymphoma from those with other diseases." (PMID 25697593, 2015).
acute liver failure (41 papers, 2010 to 2025). Rapid deterioration of liver function causing encephalopathy and coagulopathy. "During acute presentations, the patient exhibited what mimicked acute liver failure, characterized by compromised hepatic protein synthesis with decreased coagulation factors, albumin, and even failing gluconeogenesis." (PMID 39607664, 2024). "In relation to the investigated factors and poorer outcomes, acute liver failure; platelet count; albumin level; ALT, AST, and LDH activities; and CRP concentration were associated with higher mortality." (PMID 33282888, 2020). "Oral vitamin K was administered to improve the compromised coagulation, 4 units of fresh-frozen plasma and human albumin (100 ml, 20%) were given intravenously from day 2 for acute liver failure." (PMID 32019572, 2020). "These transplanted cells were able to bridge the animals through the critical period of acute liver failure, showing persistent secretion of human albumin in the rat serum throughout the observation period." (PMID 31222080, 2019). "When transplanted into mice with paracetamol-induced acute liver failure, mice sera contained human albumin and cells were able to colonize the liver." (PMID 31784643, 2019). "Using a DGAL-induced acute liver failure model, it was found that serum-derived EVs from treated rats contained significantly increased levels of albumin mRNA." (PMID 28225807, 2017). "Endotoxaemia contributes to innate immune system activation and the detoxifying function of albumin, critical to recovery from liver injury, is irreversibly destroyed in acute liver failure." (PMID 25937432, 2015). "In animal models, serum albumin decreased after acute liver failure induction, but stably returned to normal level when microencapsulated hepatocytes are transplanted." (PMID 23637958, 2013). "The concurrent measurement of both lactate and albumin provides a more comprehensive assessment of liver function and the body’s ability to cope with metabolic stress, especially in acute liver failure where both liver synthetic capacity and clearance functions are compromised." (PMID 40833444, 2025). "ADSC injection via the tail vein to rodents 1 reduced serum ALT and AST levels and mortality and 2 increased hepatic Akt and ERK1/2 phosphorylation and serum albumin levels, suggesting that ADSCs have a therapeutic effect on acute liver failure and can promote liver regeneration." (PMID 35365229, 2022). "As observed in this patient, significant elevation of hepatic enzymes, prothrombin time, and ammonia along with the reduction of serum albumin level could suggest concomitant acute liver failure, which carries a remarkably high mortality rate." (PMID 34055517, 2021). "The effect of administration of highly activated porous carbonic enterosorbents on oxidative stress manifestations and molecular conformation of serum albumin in blood of experimental animals with acute liver failure induced by carbon tetrachloride (CCl4) needs to be investigated." (PMID 32042939, 2020). "The lactate-to-albumin ratio demonstrated superior predictive performance compared to serum lactate or the lactate-to-bicarbonate ratio in identifying in-hospital complications, such as mortality, the need for mechanical ventilation, acute liver failure, and encephalitis." (PMID 41144436, 2025). "Interestingly, the therapeutic efficacy of GStemHep seems to be greater than or at least equivalent to that of primary human hepatocytes (100 vs. 60% survival, but not significantly different), which confirms that immature hepatic progenitors (AFP + ALB−) can be therapeutic for acute liver failure." (PMID 38475825, 2024). "In acute liver failure (ALF), the ANSWER study found that prolonged albumin uses decreases mortality and organ dysfunction in decompensated cirrhosis." (PMID 40585555, 2025).
acute liver failure (continued). "In this study, the remarkable increased serum ALT, AST, and TBIL levels, elongated PT, decreased serum ALB, CHE levels, increased pathological scores, and rapid death had confirmed that acute liver failure models were successfully built by D-GalN injection." (PMID 23554835, 2013). "Decreased serum albumin levels are not seen in acute liver failure because it takes several weeks of impaired albumin production until the serum albumin level drops." (PMID 21194423, 2010). "After reinitiation of cholestyramine and lactulose, sequential 20% human albumin substitution (5 × 100 ml IV), oral potassium substitution, torasemide dosage increase, and after initiation of the mineralocorticoid antagonist spironolactone (50 mg BID), her acute liver failure improved." (PMID 32019572, 2020).